HOXB2 (homeobox B2)
Diseases named in the same sentence as HOXB2 in open-access papers (continued):
Sharing a sentence is not in itself a finding about the gene and the disease.
bladder tumors (1 paper, 2010). "For four of these loci (FRZB, STAT5A, KRT13, and HOXB2), bisulfite pyrosequencing assays were able to be designed, and were used to confirm the array findings in a subset of bladder tumors examined on the array." (PMID 20808801, 2010). "HTB-9 had a HOXB2 methylation extent of 68.9, similar to what had been observed amongst primary bladder tumor samples, and thus was chosen for further examination." (PMID 20808801, 2010). "Pyrosequencing of the promoter regions of FRZB, KRT13, and HOXB2 was performed in an independent series of 263 bladder tumor patients not examined on the array as well as on 4 non-diseased tumor samples obtained from the NDRI." (PMID 20808801, 2010).
brain cancer (1 paper, 2020). A primary or metastatic malignant neoplasm affecting the brain. "Notably, there were 6 HOX genes, namely HOXA2, HOXA4, HOXB2, HOXB3, HOXB4, and HOXC4, which changed expression only in brain cancer (either in GBM, brain lower grade glioma (LGG), or in both)." (PMID 32545894, 2020).
chronic nasopharyngitis (1 paper, 2024). "Representative IHC images showed that HOXB2 protein levels were higher in NPC tissues than in chronic nasopharyngitis." (PMID 38617001, 2024).
gastric cancer (1 paper, 2020). A primary or metastatic malignant neoplasm involving the stomach. "Therefore, miR-1200 mediated the promoting role of circ_0026359 in CDDP resistance of gastric cancer cells, and the miR-1200/POLD4 and miR-1200/HOXB2 pathways might be the downstream mechanisms involved in CDDP resistance of gastric cancer." (PMID 32855967, 2020).
leukemia (1 paper, 2019). A malignant (clonal) hematologic disorder, involving hematopoietic stem cells and characterized by the presence of primitive or atypical myeloid or lymphoid cells in the bone marrow and the blood. "Following on evidence that HOXB gene upregulation occurred as an early event in NLTB-transduced CB cells, we examined RNA-seq data from established CB leukemias and a collection of T-ALL PDXs and found HOXB2/B3/B4 mRNA levels were coordinately elevated in both contexts." (PMID 31266935, 2019).
metastatic cancer (1 paper, 2024). A carcinoma which has spread from the original site of growth to another anatomic site. "This supports the notion that HOXB2 when expressed at low levels in early-stage cancer (lymph node-negative), could modulate the invasion and migration of TNBC cells and ultimately lead to metastatic cancer." (PMID 38322121, 2024).
metastatic tumors (1 paper, 2024). "In particular, the expression of HOXB2, MATN3, and ECM2 was significantly suppressed in metastatic tumors compared to that in primary tumors." (PMID 38322121, 2024). "When HOXB2 expression was low, metastasis occurred during treatment regardless of the pre-existing or newly formed metastatic tumors." (PMID 38322121, 2024).
migraine (1 paper, 2021). "For instance, we identified a new region associated with migraine at 17q21 and our DEPICT gene analysis prioritized three members of the Antp homeobox family genes (i.e., HOXB2, HOXB3, and HOXB6) at this region that encode proteins with a homeobox DNA-binding domain." (PMID 34294844, 2021).
nasopharyngeal carcinoma (1 paper, 2024). A carcinoma arising from the nasopharyngeal epithelium. "Currently, there is a lack of literature report on the relationship between HOXB2 and nasopharyngeal carcinoma, as well as its correlation with HOXB2 and radiotherapy response." (PMID 38617001, 2024).
oral cancer (1 paper, 2022). "While HOXA2 was upregulated in dysplasia but lost during the development of oral cancer, HOXB2 expression was downregulated in both dysplasia and primary tumor." (PMID 35710803, 2022).
triple-negative breast carcinoma (1 paper, 2025). An invasive breast carcinoma which is negative for expression of estrogen receptor (ER), progesterone receptor (PR), and human epidermal growth factor receptor 2 (HER2). "Similarly, the BC_P05T subcluster is characterised by elevated KRT5 expression and is primarily regulated by the transcription factor HOXB2, which restricts the occurrence of triple-negative breast cancer by reshaping the extracellular matrix." (PMID 39877290, 2025).
tumor (28 papers, 2010 to 2026). "Loss of HOXB2 expression was consistent in the potentially malignant oral lesions as well as in the primary tumor." (PMID 35710803, 2022). "In tumour xenografts derived from a range of mammary adenocarcinoma cell lines, HoxB2 was identified as a tumour repressor with changes directly evident in the mitotic index of the target cells." (PMID 41535654, 2026). "It has also been reported that estrogen can inhibit tumor growth by binding to the ERE in the HoxB2 promoter region through its receptor ERα." (PMID 39706274, 2025). "Overall, our results indicate a tumor-suppressive role of HOXB2 by maintaining ECM organization and delineate potential clinical utility of HOXB2 as a marker for TNBC patients." (PMID 38322121, 2024). "In conclusion, our study provides the first preliminary evidence that HOXB2 acts as a tumor promoter in NPC progression and enhances radioresistance by regulating FOXO1 expression." (PMID 38617001, 2024). "Previous studies have reported that HOXB2 functions as either a tumor suppressor or an oncogene in several types of tumors." (PMID 38322121, 2024). "On day 58, the mean tumor volume was 131.82 ± 13.18 mm3 and 27.29 ± 4.8 mm3 for the control and HOXB2-overexpressing groups, respectively." (PMID 38322121, 2024). "HOXB2 is a member of the B cluster of homeobox transcription factors localized on chromosomes 17 that acts as either an oncogene or tumor suppressor with tissue-specific regulation." (PMID 38617001, 2024). "HOXB2 was reported to be a negative regulator of tumor growth, and its overexpression inhibited the growth of MDA-MB-231." (PMID 38203393, 2023). "The relationship between HOXB2 expression and cancer progression has been reported in several studies, and HOXB2 has been shown to have bifunctional roles, as an oncogene and as a tumor suppressor gene." (PMID 28465481, 2017). "HOXB2 expression was reduced in both dysplastic and primary tumour samples." (PMID 41477365, 2025). "Moreover, the inactivation of HOXB2 or activation of FOXO1 are potential strategies to inhibit tumor progression and overcome radioresistance in NPC." (PMID 38617001, 2024). "Recent studies suggest that HOXB2 participates in tumor development and progression." (PMID 38617001, 2024). "The HOXB2 expression was downregulated in both the dysplasia as well as the primary tumor samples." (PMID 35710803, 2022). "Moreover, the abnormal expression of HOXB2 was related to tumor size, TNM stage and lymph node metastasis in ESCC patients (P < 0.05)." (PMID 32633082, 2020). "Consequently, the HOXB2 inactivation or FOXO1 activation may be potential strategies to inhibit tumor progression and overcome radioresistance in NPC." (PMID 38617001, 2024). "Among these, the top three TFs—NFIC, HOXB2, and BCL6—demonstrated notably high expression in tumor cells." (PMID 40190189, 2025). "We demonstrated that forced expression of HOXB2 in TNBC cells suppresses invasive and migratory characteristics in vitro along with the suppression of tumor growth and metastasis in vivo." (PMID 38322121, 2024). "We further distinguished between tumour cells and non‐malignant epithelial cells using several marker genes, including MMP7, MMP9, MMP13 and HOXB2." (PMID 36588094, 2023). "We found that, in addition to interacting with CD2, CD58 was co-expressed and physically interacted with HOXB family genes (HOXB2, HOXB3, and HOXB5), AKAP12, CLIC1, CPNE3, etc., which were reported to be involved in tumor initiation and progression." (PMID 34193136, 2021). "Additionally, HOXB2 and HOXB7 are highly expressed in C1, C2, and C6 subtypes, which also indicates that they play a role in promoting tumor progression." (PMID 39980564, 2025).
tumor (continued). "Real-time qPCR and western blot analyses confirmed the lower expression levels of HOXB2 in TNBC than in non-TNBC cell lines, further indicating a role for HOXB2 in tumor aggressiveness." (PMID 38322121, 2024). "For each patient, HOXD10 and HOXD11 but not HOXB2 mRNA expression was gradually elevated in LM, PCA and N tissues, indicating the oncogenic potential of tumor aggressiveness in PSCC." (PMID 36151071, 2022). "Interestingly, we observe that non-diseased bladder epithelium exhibits a similar extent of methylation at HOXB2 and KRT13 as the non-invasive disease, while at FRZB the non-diseased tissue has a significantly lower extent of methylation than either of the 2 tumor types." (PMID 20808801, 2010).
cancer (18 papers, 2007 to 2025). A tumor composed of atypical neoplastic, often pleomorphic cells that invade other tissues. "From our identified loci, IGF2BP1 and RAD51L1 have been implicated in cancer as have HOXB2, 2q35, and HMGA2." (PMID 20195514, 2010). "One member of this family, the homeobox protein Hox-B2 (HOXB2), has been found to enhance the malignant behavior of malignant cells, thus playing an essential role in cancer progression." (PMID 40535133, 2025). "Among these HOX genes, HOXB2 is best known for contributing to tumorigenesis in multiple cancers such as breast, lung, cervical, and esophageal cancer." (PMID 38322121, 2024). "Further studies are needed to clarify the functional role of HOXB2 in cancer." (PMID 34184409, 2021). "Among these, there were known regulators such as HOXB2 and KLF4 in Cancer LumA, as well as HMGA1 in Cancer Basal." (PMID 40397381, 2025). "Reduction of HOXB2 and the HOXB2/MATN3/ECM2 transcriptional axis correlated with poor survival in patients with various cancers." (PMID 38322121, 2024). "Through VENN analysis, we detected 603 upregulated and 1043 downregulated DEGs overlapping in the three cancer cell lines, including 16 upregulated TFs (e.g., HOXA2, HOXB2, HOXC10, and NKX2-1) and 36 downregulated TFs (e.g., BACH1 and CDX1), respectively." (PMID 32156290, 2020). "This suggests that HOXB2 may upregulate NUSAP1 expression through activation of the PI3K/Akt signaling pathway, consequently promoting cancer cell proliferation, invasion, and migration." (PMID 40535133, 2025). "To assess whether cancer progression is regulated by HOXB2 in vivo, we injected MDA-MB-231:Emp.Vec and MDA-MB-231:HOXB2 cells subcutaneously into the mammary fat pads of BALB/c nude mice." (PMID 38322121, 2024). "We further demonstrated that HOXB2 modulated the expression of long non-coding RNA DANCR, a differentiation antagonizing non-protein coding RNA, and thus influenced its downstream effectors ABCA1, ABCG1, and ERK signaling to boost drug resistance and cancer proliferation." (PMID 38851728, 2024). "Additionally, our findings suggest that the lack of HOXB2 subsequently downregulates MATN3 and the ECM2 downstream transcriptional network, leading to aggressive cancer progression, EMT-like characteristics, and poor prognosis." (PMID 38322121, 2024).
hematological neoplasms (1 paper, 2024). "Furthermore, in MSCs from all hematological neoplasms, we observed an overexpression of HOXA2 and HOXA3 as well as HOXB2-8 genes, which are crucial for hematopoietic cell fates and skeletal development." (PMID 38893194, 2024).
HOXB2 also shares sentences with these, for which no sentence is quoted: acute myeloid leukemia (3 papers); colorectal cancer (3); esophageal squamous cell carcinoma (3); clear renal cell carcinoma (2); mammary adenocarcinoma (2); cervical cancer (1); colon cancer (1); craniosynostosis (1); embryonal carcinoma (1); hepatocellular carcinoma (1); human papillomavirus infection (1); infection (1); liver cancer (1); lymph node metastasis (1); malignant lymphoma (1); melanoma (1); neuroblastoma (1); pancreatic neuroendocrine neoplasm (1); squamous cell carcinoma (1).